TLR7 (toll like receptor 7)
Diseases named in the same sentence as TLR7 in open-access papers (continued):
Sharing a sentence is not in itself a finding about the gene and the disease.
glomerulonephritis (28 papers, 2011 to 2025). A renal disorder characterized by damage in the glomeruli. "Compared with Tlr7+/+ Tlr9–/– mice, Tlr779/779 Tlr9–/– mice demonstrated a dramatic amelioration of lupus disease, as evidenced by reduced splenomegaly, glomerulonephritis (GN) and interstitial nephritis (IN) scores." (PMID 40794441, 2025). "At 15–16 weeks of age, compared with Cybb-KO mice, Tlr7 and Cybb double-KO mice had significantly reduced proteinuria and glomerulonephritis." (PMID 39042716, 2024). "Strikingly, all parameters of SLE, including proteinuria, glomerulonephritis, and interstitial nephritis were significantly improved in both males and females when TLR7 was specifically and only deleted in B cells on a global Cybb-deficient background." (PMID 39042716, 2024). "Mice overexpressing TLR7 from a BAC Tg had ameliorated glomerulonephritis and reduced germinal centers when pDC function was impaired via haploinsufficiency of Tcf4, implying a role for pDCs." (PMID 37606042, 2023). "TLR7 activity mediates the formation of anti-RNA autoantibodies and glomerulonephritis in MRL/lpr mice as well as in pristane-induced SLE." (PMID 29650017, 2018). "Both the Yaa, derived from SB/Le mice, and TLR7 transgenic models show an increase in the gene copy number and expression of TLR7, which results in a lupus-like disease marked by lymphocyte hyperactivation, ANAs and glomerulonephritis." (PMID 25147296, 2014). "TLRs are also implicated in the initiation of disease in MRL/lpr mice, because a TLR7/TLR9 double mutant protects the mouse from glomerulonephritis and lowers autoantibody production." (PMID 25147296, 2014). "Female 564Igi Tlr7/9−/− mice with two normal X chromosomes, and hence two functional copies of Tlr8, produce autoantibodies, express Ifn-I in neutrophils, have expanded populations of granulocytes, and ultimately develop glomerulonephritis." (PMID 26441962, 2015). "However, compared with Tlr9+/–Tlr7–/– MRL/lpr mice, Tlr997Tlr7–/– mice had markedly exacerbated lupus disease, with increased spleen weight and higher glomerulonephritis and interstitial nephritis scores." (PMID 40794441, 2025). "Moreover, MDSCs generated the enhanced reactive oxygen species (ROS) via TLR-7 activation in vivo or in vitro, since TLR-7 is thought to trigger glomerulonephritis in experimental lupus erythematosus." (PMID 29988544, 2018). "However, TLR8 deletion of C57BL/6 genetic background triggers anti-dsDNA antibody secretion and glomerulonephritis, an effect abrogated by co-deletion of TLR7 suggesting rather an immunoregulatory role of TLR8 in TLR7." (PMID 29650017, 2018). "TLR7-mediated IFN-α production in active SLE with glomerulonephritis showed higher tendency than those without glomerulonephritis." (PMID 30210502, 2018). "In addition, Tlr7, another nucleic acid sensors located in endosomes, has also been shown to contribute to IgG and ANA production as well as kidney IC deposition and glomerulonephritis in pristane-induced disease in C57BL/6 wt mice." (PMID 27760209, 2016). "Consequently, ABIN1[D485N] × TLR7 KO mice did not display increased levels of dsDNA antibodies or Igs, and glomerulonephritis was also strongly suppressed." (PMID 31694920, 2019).
nephritis (25 papers, 2012 to 2026). Inflammation of renal tissue. "B cell–intrinsic Tlr7 deficiency is sufficient to ameliorate severe nephritis in Cybb-deficient mice." (PMID 39042716, 2024). "Our data revealed that Tlr7 signaling is primarily pathogenic in females, as evidenced by decreased nephritis, diminished B and T cell populations associated with disease, and reduced serum IgG titers in Tlr7-deficient pSD females." (PMID 39310226, 2024). "The authors suggest controlling TLR7 levels within myeloid populations to prevent chronic inflammation and severe nephritis in patients predisposed to SLE." (PMID 39000140, 2024). "The present work also showed a strong association between TLR7 rs3853839 genotypes and alleles with nephritis." (PMID 36439744, 2022). "Most-importantly, deficiency of TLR7 ameliorates SLE-associated splenomegaly and nephritis, while expression of an extra copy of TLR7 exacerbates it." (PMID 31354738, 2019). "It follows that TLR7-stimulated B6 mice, which had minimal/trace proteinuria, also died from a non-nephritis related cause." (PMID 31998321, 2019). "While TLR7 hyper-responsiveness in human SLE is consistent with the TLR7-associated nephritis shown by mouse models, the role of TLR9 remains controversial." (PMID 25538618, 2014). "Also, TLR7 rs3853839 genotypes and alleles were significantly associated with nephritis, arthritis, oral ulcers, and thrombocytopenia." (PMID 36439744, 2022). "In our work, all genotypes and alleles TLR7-rs3853839 were associated with nephritis (CC vs CG P < 0.0001, OR 0.13, 95% CI 0.05–0.35/CC vs GG = 0.04, OR 0.10, 95% CI 0.01–0.87/CC vs CG + GG, P < 0.0001, OR 0.12, 95% CI 0.05–0.32/C vs G P = 0.0001, OR 0.21, 95% CI 0.10–0.47)." (PMID 36439744, 2022). "A moderate increase in TLR7 is sufficient for developing nephritis, while the normalization of B cell TLR7 expression or temporary pDCs depletion slows the progression of LN." (PMID 37894915, 2023). "In the investigated Egyptian cohort, our findings suggest that TLR7 rs3853839 gene polymorphisms increase the risk for SLE development and play a role in developing clinical characteristics, especially nephritis." (PMID 36439744, 2022). "Macrophage-specific Tnip1 deletion is sufficient for nephritis to develop in Tnip1-/- mice, and high levels of TLR7 were expressed in patrolling monocytes of NZBWF1 mice." (PMID 34868046, 2021). "Moreover, Tlr7 exacerbates nephritis in females, while Tlr7-mediated signals protect against pulmonary inflammation in pSD males." (PMID 39310226, 2024). "TLR7 was significantly upregulated in mice with moderate and severe nephritis, and TLR9 was significantly upregulated in moderate nephritis." (PMID 29190833, 2017). "TLR9 inhibition even neutralized the beneficial effects of the TLR7 blockade on systemic autoantibody levels without affecting the effects of the TLR7 blockade on nephritis." (PMID 29650017, 2018). "Deletion of TLR7 in MRL/lpr mice has been shown to reduce antibody production and nephritis." (PMID 29052537, 2017). "Ablation of Tlr7 did not alter the degree of nephritis male mice." (PMID 39310226, 2024). "Our results advocate those genetic variations of TLR7 rs3853839 may be considered biomarkers for the expectation of SLE phenotypes and may help develop new therapeutic interventions that may prevent the clinical complications of SLE, especially nephritis." (PMID 36439744, 2022). "Although a study has shown that Toll-like receptor 7 (TLR7) -mediated LN is independent of IFN-I signaling, it is not enough to mask the ultimate role of IFN-I in nephritis acceleration." (PMID 33959133, 2021). "The qPCR analyses revealed that TLR7 and TLR 8 were up-regulated in class IV nephritis, although without reaching statistical significance." (PMID 22479529, 2012).
malaria (24 papers, 2011 to 2025). Malaria is a serious and sometimes fatal disease caused by a parasite that commonly infects a certain type of mosquito which feeds on humans. "Iron accumulated in the spleen, and the iron content of erythroid cells and splenic macrophages were less in TLR7-/- infected mice than in wild-type infected mice, suggesting that TLR7 is associated with iron metabolism in malaria." (PMID 37180169, 2023). "Among biomarkers that were significantly associated with PME, GM-CSF TLR7/8 crude was associated with a risk of developing clinical malaria during the first year of life, which is in contrast with previous observations, but in agreement with others." (PMID 30384846, 2018). "It is unclear whether studies in endemic areas that have assessed association of TLRs have investigated the role of TLR7 in malaria susceptibility/resistance." (PMID 30619355, 2018). "While the involvement of TLR9, TLR4, and TLR2 in malaria immunity/pathology is evident from studies in both mouse malaria models and in humans, thus far none of the studies in endemic areas have revealed the association of TLR7 with human malaria immunity/pathology." (PMID 30619355, 2018). "Similarly, TLR7 rs179008 & rs5743836 are associated with cancer, malaria, HCV, and tuberculosis." (PMID 34113509, 2021). "In addition, certain biomarkers, which levels were significantly modified depending on the PME category, were independent predictors of either malaria risk (GM-CSF TLR7/8 crude) or protection (IL-12 TLR7/8 ratio and IP-10 TLR3 crude, IL-1RA TLR7/8 ratio) during the first year of life." (PMID 30384846, 2018). "This study aimed to evaluate the association between polymorphisms in TLR1, TLR4, TLR7, TLR8, TLR9 and TIRAP and the clinical manifestations of malaria caused by P. vivax in a population from the Amazon region of Pará, Brazil." (PMID 40963451, 2025). "In our study, we attempted to investigate the effect of TLR7 on malaria-induced splenic erythropoiesis in P. yoelii-infected C57BL/6 mice." (PMID 37180169, 2023). "Remarkably, in infants from this cohort TLR7/8-induced IL-1RA production in cord blood was an independent predictor of malaria protection during the first year of life." (PMID 33593344, 2021). "Further studies have reported that IFN-γ release during murine malaria occurs downstream of TLR7 and TLR9 signaling and is thus dependent on the sensing of Plasmodium-derived nucleic acids." (PMID 30972055, 2019). "For example, higher concentrations of GM-CSF and eotaxin following TLR7/8 stimulation, of IL-1β following TLR9 stimulation, and of IL-7 following IL-3 stimulation, were associated with an increased hazard of malaria in the first year of life." (PMID 30454004, 2018). "Here, we found that Th1 cytokines and chemokines (IL-12 TLR7/8 ratio and IP-10 TLR3 crude) and cytokines induced upon inflammation (IL-1RA TLR7/8 ratio) were associated with a decreased risk of clinical malaria during the first year of life." (PMID 30384846, 2018). "This is because, although RNA of human malaria parasite P. falciparum has been reported to induce cytokine responses through TLR7 recognition, the reported activity appears to be very low." (PMID 30619355, 2018). "Altogether, these data establish pDCs as key producers of type I IFN in the course of severe malaria, through the TLR7/MyD88 pathway." (PMID 27792766, 2016). "Therefore, this study aimed to analyse the potential influence of variants of TLR1, TLR4, TLR7, TLR8, TLR9 and TIRAP on the clinical manifestations of malaria caused by P. vivax in the Amazon region of Brazil." (PMID 40963451, 2025). "This study may give us an insight into the relationship between TLR7-induced inflammatory response and malaria-induced splenic erythropoiesis and promote the development of a therapeutical strategy based on the target of TLR7." (PMID 37180169, 2023). "These also highlighted that TLR7 regulated the malaria-induced splenic erythropoiesis with iron." (PMID 37180169, 2023).
malaria (continued). "Moreover, the mechanism through which TLR7 regulates malaria-induced splenic erythropoiesis was explored as well." (PMID 37180169, 2023). "Meanwhile, TLR7-/- infected mice exhibited more severe malaria-induced anemia." (PMID 37180169, 2023). "It demonstrated that IL21R was expressed in healthy individuals in malaria-endemic areas before the start of the malaria season and down-regulated a week after treatment of the first acute malaria episode (in convalescence), while TLR7, TLR9, PRDM1, and CD38 showed the opposite pattern." (PMID 36380692, 2022). "As TLRs have been shown necessary in the process of priming for induction of pro-caspase-11 and TLR7 as well as TLR9 are strongly activated by infection with malaria parasites, we investigated the role of NAS-TLRs on activation of the noncanonical inflammasome pathway." (PMID 32929083, 2020). "However, the clinical relevance of TLR-mediated immune responses in the susceptibility to malaria has been mainly reported for endosomal PRRs such as TLR3, TLR7/8, and TLR9 in African children." (PMID 30384846, 2018). "Two recent studies by using lethal malaria model of P. yoelii YM infection, in which parasites grow rapidly to attain peak parasitemia of ~80% by 6 days postinfection, have also showed TLR7-dependent peak levels of type I IFN production at 24–36 h postinfection." (PMID 30619355, 2018). "While it is clear that RNA induced TLR7 signaling plays an important role in early type I IFN production in mouse malaria, it remains unclear whether or to what extent RNA of human parasites is able to induce type I IFN response." (PMID 30619355, 2018). "As such, our observations support a model in which processed fragments of YRNA4 (HY4) in exosome-like vesicles released by erythrocytes infected with malaria could mediate activation of distant monocytes by stimulating the TLR7/8 signaling pathway." (PMID 29425228, 2018). "Our present study that demonstrates that TLR7 modulates splenic erythropoiesis in malaria gives an insight into the relationship between phagocytosis of iRBCs and splenic erythropoiesis and suggests that TLR7 plays multiple roles in malaria which is a potential target of therapies in malaria." (PMID 37180169, 2023). "In malaria blood-stage infection, parasite DNA, RNA and GPI anchors interact with TLR9, TLR7 and TLR2, respectively." (PMID 41398915, 2025). "Specifically, TLR agonists such as those targeting TLR7/8 have shown promise in enhancing the immunogenicity of vaccines against severe diseases like cancer, AIDS, and malaria by linking innate with adaptive immune responses." (PMID 38732254, 2024). "TLR7 and TLR9 have been reported to contribute to innate immune sensing during blood-stage infection in murine malaria models." (PMID 30972055, 2019). "As such, studies in various mouse models have demonstrated that TLR9, TLR7, TLR4, and TLR2 play important roles in malaria immunity and cerebral, placental and other severe malaria pathology." (PMID 30619355, 2018). "However, pDCs produce type I IFN via TLR7/MyD88 in the bone marrow, and type I IFN activates inflammatory monocytes and NK cells in the blood, which is a lethal factor in severe malaria (Plasmodium yoelii YM infection)." (PMID 37180169, 2023). "Thus, taken together, these results show that TLR7 sensing in pDC is required for their arrest and potential interactions with CD169+ MP in the BM of malaria-infected mice at the time pDC produce peak type I IFN." (PMID 36278864, 2022). "Using a mouse model of severe malaria, we have previously established that upon priming by CD169+ macrophages (MPs), pDC initiates type I IFN-I secretion in the bone marrow (BM) of infected mice via cell-intrinsic TLR7 sensing and cell-extrinsic STING sensing." (PMID 36278864, 2022). "TLR1, TLR2, TLR4, TLR6, TLR7 and TLR9 have been reported to recognize malaria ligands." (PMID 33344264, 2020). "TLR7 and MDA5 are the major sensors for malaria parasite RNA for IFN-I responses." (PMID 33344264, 2020).
malaria (continued). "Additionally, following TLR7/8 stimulation, samples obtained from infants of mothers with placental malaria were hyper-responsive compared to those without evidence of prenatal malaria exposure." (PMID 30454004, 2018). "However, since P. falciparum RNA appears to have very low immunostimulatory activity, it is possible that TLR7 has either minor or no role in human malaria." (PMID 30619355, 2018). "Indeed, mice bearing non-functional TLR9 or MyD88, or treated with a TLR7/TLR9 antagonist display a less pronounced inflammatory response and attenuated pathology during experimental malaria." (PMID 24453977, 2014).
pancreatic cancer (24 papers, 2015 to 2025). "In the pancreatic cancer model, TLR7 signaling through STAT3 results in loss of PTEN, p16, and cyclin D1, which leads to tumor development." (PMID 38850110, 2024). "Moreover, our results indicated that TLR7 and -8 expression is associated with tumor cell growth and tumor progression in both colon and pancreatic cancer." (PMID 27941651, 2016). "To analyze whether inflammation in pancreatic cancer was associated with TLR7 and TLR8 expressing cancer cells, we dissected the expression of COX-2 in the pancreatic tumor cells by immunohistochemical staining and western blot analysis." (PMID 26134824, 2015). "In the course of this study, we further identified a subset of TLR7 expressing pancreatic cancer cell lines." (PMID 36602302, 2023). "There are conflicting reports regarding the expression pattern and function of TLR7 in pancreatic cancer." (PMID 36602302, 2023). "To investigate the functional role of TLR7 expression in pancreatic cancer cells, we treated TLR7‐high human Lon560 and murine KC623 cells with the well‐established inhibitor IRS‐954." (PMID 36602302, 2023). "Here, we show that TLR7 is expressed and activated in pancreatic cancer cells in vitro and in vivo and promotes the proliferation of tumor cells." (PMID 36602302, 2023). "A study on the expression and prognostic value of TLRs in pancreatic cancer patients treated with neoadjuvant therapy demonstrated that both TLR7 and TLR9 predicted a favorable postoperative outcome in a separate analysis adjusted for background variables." (PMID 36476317, 2022). "Compared to earlier stages and chronic pancreatitis, the expression of TLR7/TLR8 was increased in stage I-IV pancreatic cancer, which was upregulated in a stage-dependent manner in advanced tumors." (PMID 36476317, 2022). "Functional analysis in human pancreatic cancer cells points to a significant role of both TLR7 and TLR8 in chronic inflammation-mediated signaling transduction, leading to tumor cell proliferation and chemoresistance." (PMID 36476317, 2022). "In pancreatic cancer, TLR7 expression was markedly increased in the progression from PanINs to metastatic cancer both in humans and mice." (PMID 34884547, 2021). "Of these, TLR7 seems to be the most important, as its expression is almost inexistent in healthy pancreas, but it is present in pancreatic tumor tissue and in pancreatic cancer cell lines." (PMID 33925979, 2021). "Another reported TLR7/8 agonist is Resiquimod (R848), which plays a role in the remodeling of pancreatic cancer immune microenvironment and is responsible for the activation of an anti-tumor response." (PMID 34884547, 2021). "R848-stimulation of TLR7/8 overexpressing pancreatic cancer cell line resulted in increased cell proliferation and reduced chemosensitivity." (PMID 31695691, 2019). "We conclude that inflammation-mediated progression, tumor survival, metastatic potential and mediation of chemoresistance are closely associated with TLR7 and TLR8 expressing pancreatic cancer cells." (PMID 26134824, 2015). "In general, TLR7 expression of pancreatic cells in all analyzed subjects with pancreatic cancer and with chronic pancreatitis was more intense than TLR8." (PMID 26134824, 2015). "Determination of the tumor growth showed a significant increase in tumor volume of TLR7+ PANC1 pancreatic tumors in contrast to empty vector PANC1 tumors (P<0.005)." (PMID 26134824, 2015). "Functional analysis in human pancreatic cancer cells point to a significant role of both TLRs in chronic inflammation-mediated TLR7/TLR8 signaling leading to tumor cell proliferation and chemoresistance." (PMID 26134824, 2015). "Expression of TLR7/TLR8 in UICC stage I–IV pancreatic cancer, chronic pancreatitis, normal pancreatic tissue and human pancreatic (PANC1) cancer cell line was examined." (PMID 26134824, 2015).